ENSG00000284057 (novel protein, C11orf54-MED17 readthrough)
Gene: Protein-coding gene on chromosome 11 (93,741,664 to 93,812,378, forward strand). Ensembl gene ENSG00000284057.
Genetic constraint (gnomAD): Loss-of-function variants: 51 observed, 86.74 expected, observed/expected ratio (o/e) 0.59, 90% interval 0.47 to 0.74. Missense variants: 768 observed, 862.81 expected, observed/expected ratio (o/e) 0.89, 90% interval 0.84 to 0.94. Synonymous variants: 277 observed, 286.38 expected, observed/expected ratio (o/e) 0.97, 90% interval 0.88 to 1.07.